EGFR (epidermal growth factor receptor)
Diseases named in the same sentence as EGFR in open-access papers (continued):
Sharing a sentence is not in itself a finding about the gene and the disease.
lung cancer (continued). "Therefore, we integrated the mRNA levels of BZW1 and EGFR with the survival curves of online lung cancer databases." (PMID 31601833, 2019). "Examples of cancers that exhibit increased EGFR expression along with disease progress and do not respond to TKIs include prostate cancer, ovarian cancer, pancreatic cancer, colorectal cancer, head and neck cancer, cervical cancer, and lung cancers expressing wild-type EGFR." (PMID 31508364, 2019). "A less stringent threshold (RSA ≤ −3 and Q3 z-score ≥1) expanded the list to 171 genes, including negative regulators of YAP signaling such as NF2/Merlin and SAV1, further warranting the importance of YAP signaling in mediating EGFR TKI resistance in lung cancer." (PMID 31741433, 2019). "Therefore, it is vital to explore the molecular mechanism through which HER3 expression is regulated in EGFR-positive lung cancers." (PMID 31619200, 2019). "Interestingly, we found that FAM83A but not FAM83B was downregulated in tumors bearing KRAS mutations as the EGFR mutation, KRAS mutation, and ALK rearrangement are largely mutually exclusive events in lung cancer." (PMID 31242643, 2019). "Besides, the overexpression of EGFR has been found in several epithelial malignancies, including lung cancer (approximately 40–80 % of NSCLC)." (PMID 31217907, 2019). "Furthermore, the combination of WA and chemotherapeutic drugs, including cisplatin and pemetrexed, exerted synergistic effects on the inhibition of epidermal growth factor receptor (EGFR) wild-type lung cancer cell viability." (PMID 31319622, 2019). "The translational research on liquid biopsy in EGFR-mutated lung cancer is still debating how a negative result should be interpreted." (PMID 31861832, 2019). "The advent and use of EGFR TKIs have revolutionized treatment for advanced lung cancer." (PMID 31699150, 2019). "Exon 20 Thr790Met substitution (T790M), affecting the ATP binding pocket of the EGFR kinase domain, accounts for approximately half of all lung cancer cases with acquired resistance to the current first generation EGFR tyrosine kinase inhibitors, erlotinib and gefitinib." (PMID 31816897, 2019). "To define the role of METex14 in mediating resistance to EGFR TKIs, we generated two isogenic EGFR-mutant non–small-cell lung cancer (NSCLC) cell models using PC9 (exon 19 deletion) and H1975 cells (L858R and T790M) by transduction with lentiviral vectors driving expression of METex14." (PMID 31157314, 2019). "In lung cancer cells lines the modified EMT conferred resistance to anti-EGFR agents." (PMID 31443300, 2019). "The epidermal growth factor receptor (EGFR) is highly expressed in lung cancers." (PMID 30790152, 2019). "Therefore, targeting STAT3 is considered a potential strategy for overcoming EGFR-TKI resistance associated with KRAS and T790 M mutations in lung cancers." (PMID 31619200, 2019). "Additional genetic aberrations are frequent in EGFR-mutant lung cancer and may mediate innate and AR to third-generation EGFR TKIs." (PMID 32914023, 2019). "Collectively, these findings indicate DUOX1 silencing in lung cancer cells impacts on EGFR internalization and nuclear translocation in response to EGF, with corresponding consequences for EGFR-mediated cell proliferation and migration, as well as sensitivity to (antibody-based) EGFR targeting." (PMID 30890751, 2019). "The impact of EGFR and KRAS mutations in Brazilian lung cancer remains poorly explored." (PMID 30824880, 2019). "Statins might also enhance the therapeutic effects and overall survival in lung cancer patients receiving epidermal growth factor receptor-tyrosine kinase inhibitor (EGFR-TKI) therapy." (PMID 31892709, 2019). "Finally, CAR10 binds to and stabilizes YB-1, leading to the upregulation of EGFR in lung cancer and promoting proliferation." (PMID 31632972, 2019). "It has already been shown in lung cancer that EGFR pathway activation could induce PD-L1 expression." (PMID 31514305, 2019).
lung cancer (continued). "EGFR targeted therapies have been successful in the treatment of advanced lung cancer." (PMID 30886831, 2019). "Therefore, in this study, we focused on evaluating the function of SCD1 in the treatment of EGFR-targeted lung cancer." (PMID 31019378, 2019). "Expression of ABCG2 has been reported in both lung cancer and breast cancer, suggesting that it may influence tumor resistance and the pharmacokinetics of EGFR TKIs." (PMID 31340525, 2019). "Mutations in the epidermal growth factor receptor (EGFR) gene, associated with lung adenocarcinoma pathogenesis, have been linked to the presence of old pulmonary tuberculosis (TB) lesions in patients with lung cancer." (PMID 32039196, 2019). "Generally, female patients have a high proportion of EGFR-positive lung cancer." (PMID 30653558, 2019). "The results found that the lung cancer cells had high levels of activated EGFR/PI3K/AKT signaling." (PMID 31019378, 2019). "Consequently, several candidates (like Epidermal Growth Factor Receptor (EGFR) for lung cancer) have been developed as molecular targets for personalized medicine." (PMID 31340863, 2019). "Unlike lung cancer, with EGFR mutations mainly in the kinase domain, GBM exhibits EGFR mutations mainly in the extracellular domain." (PMID 31122294, 2019). "Notably, a recent study identified a similar gene expression program in EGFR-mutant lung cancer following treatment with EGFR inhibitors." (PMID 30990165, 2019). "Although EGFR TKIs are potent in inhibiting the kinase activity of wild-type EGFR, cancers expressing wild-type EGFR, such as lung cancer, head and neck cancers, prostate cancer, and ovarian cancer, do not respond to TKIs regardless of the expression level of EGFR." (PMID 31508364, 2019). "In this study, we found that GK5 is upregulated in specimens of lung cancer resistant to EGFR-TKIs." (PMID 30791926, 2019). "In the adjusted model which was modified for age, sex, premium level, comorbidities, anti-neoplastic agents, cancer treatments, CT regimen before EGFR-TKI and concomitant drugs, lung cancer patients with COPD still remained at a higher risk of death (HR 1.05, 95% CI 1.01–1.08, p = 0.012)." (PMID 31336878, 2019). "Accumulating evidence suggests that small subpopulations of cancer cells can survive strong EGFR inhibition by entering a DTP state, which could allow the emergence of heterogeneous EGFR TKI resistance mechanisms in EGFR-mutant lung cancers." (PMID 31741433, 2019). "Finally, classical (CL) glioblastoma, characterized by high-level EGFR amplification events, not only shares a common oncogenic alteration with Her2+ breast cancer brain metastases, but also with EGFR-amplified lung cancer brain metastases." (PMID 31632393, 2019). "Thus, EGFR and its signaling components can be used as targets in the development of new drugs for lung cancer treatment." (PMID 31636509, 2019). "The authors synthesized an epidermal growth factor receptor targeted PEGylated iron oxide nanoparticles (IONPs) for targeted delivery and imaging to lung cancer in an in vitro and in vivo rat xenograft model of human lung cancer (H460)." (PMID 31035440, 2019). "While NSCLC patients with EGFR and ALK mutations show relatively improved survival compared with those with wild-type EGFR and ALK22,23, determining the prognostic value of the PLR in wild-type EGFR and ALK lung cancer would be meaningful." (PMID 30886226, 2019). "In addition to this, KDM5A was also shown to mediate resistance to a second EGFR inhibitor, called gefitinib, in EGFR-mutant lung cancer cell lines." (PMID 35582714, 2019). "At the same time, a previous report suggested that the better prognosis of female lung cancer patients could also be attributed to the better response to EGFR inhibitor treatment for females." (PMID 31653236, 2019).
lung cancer (continued). "The main reason for the favorable outcome in non-smokers is the occurrence of certain molecular subtypes (oncogene-addicted lung cancer), enabling the specific treatment with Previous epidermal growth factor receptor-tyrosine kinase inhibitors (EGFR-TKIs) or other agents." (PMID 30744199, 2019). "We chose to focus on 4 lung cancer cell lines, H292, A549, H187, and H460, which all express EGFR at comparable levels and are not known to contain any EGFR mutations." (PMID 30890751, 2019). "Results showed that the combination of IPA-3 plus auranofin abrogated the expression of total/phosphorylation of PAK1, PKCι, ERK 1/2, mTOR, AKT, and YAP1 in the 3 lung cancer cell lines studied HCC827 (EGFR-mutant LUAD), H23 (KRAS-mutant LUAD) and H520 (PAK1 overexpression)." (PMID 31660987, 2019). "Our data suggest that therapeutic delivery of miRNA-145 may be considered as a new remedial approach to overcome the EGFR-TKIs resistance in lung cancer cells." (PMID 31554377, 2019). "EGFR is, therefore, an important potential target for lung cancer therapy." (PMID 31185703, 2019). "Four cell lines, lung cancer PC9 cells (EGFRL858R+ and FGFR1−), lung cancer H520 cells (EGFR− and FGFR1+), lung cancer H1975 cells (EGFRL858R/T790M+ and FGFR1+), and normal lung epithelial cells Beas-2B cells (EGFR+ and FGFR1+), were chosen for the cytotoxic assay." (PMID 31998131, 2019). "PD-1 axis inhibitors have been shown to modestly prolong survival of mice with EGFR mutant lung cancer, however, whether in combination with erlotinib this translates into improved survival and/or delays the emergence of resistance is unknown." (PMID 31291990, 2019). "Indeed, EGFR inhibition by gefitinib has previously been shown to induce senescence in lung cancer cells." (PMID 30743996, 2019). "Several Brazilian studies have evaluated whether anti-EGFR TKIs are cost-effective for treating lung cancer." (PMID 32159636, 2019). "In addition, the mean progression‐free duration of the pleural effusion in EGFR mutant lung cancer was 480 (range 306–654) days, while those with EGFR wild type lung cancer was 169.5 (range 146–193) days." (PMID 31389192, 2019). "Interestingly, pleural effusion in patients with EGFR mutant lung cancer was found to be controlled longer, and patients with good response within 12 weeks had delayed progression of pleural effusion after disease progression." (PMID 31389192, 2019). "In the past decade, EGFR-TKIs yield significant success in the treatment of lung cancer." (PMID 30842489, 2019). "Similarly, an only modest effect of CK2 inhibition was recently reported in KRAS-active non–small cell lung cancer cells resistant to EGFR inhibitors." (PMID 31277672, 2019). "The MDS results for the ΔELREA mutation are also consistent with the effects of compounds that inhibit EGFR mutant cell lines: inhibitors recognizing the active conformation are more effective against the ΔELREA mutant in lung cancer cell lines as compared to cell lines expressing wild-type EGFR." (PMID 31536605, 2019). "Study of Cul4A in NSCLS shows that Cul4A overexpression promotes docetaxel and doxorubicin resistance in lung cancer cells, it may attribute to EGFR transcriptional expression and antiapoptosis of NSCLC cells regulated by Cul4A10." (PMID 30718461, 2019). "In addition, a study in mouse models of EGFR mutant lung cancer reported increased leukocyte infiltration and enhanced antigen-presenting capabilities after 24 h of erlotinib treatment." (PMID 31291990, 2019). "Thus, a better understanding of EGFR-regulated signaling pathways or other molecular mechanisms related to EGFR signaling is likely to have important clinical significance in cancer therapy for lung cancer patients." (PMID 31588184, 2019). "We propose that BBI608, which was selected from a panel kit, and YM155 are potential therapeutic agents against EGFR-positive lung cancers and may be combined with EGFR-TKIs for application in the eradication of lung cancers." (PMID 31619200, 2019).
lung cancer (continued). "In the case of EGFR mutant lung cancer, where there are concerns about combining TKIs with immunotherapies, like immune checkpoint inhibitors due to toxicity, it is possible that other agents that lead to tumor regression could be used." (PMID 31291990, 2019). "From May 1, 2013, to May 31, 2016, 658 patients with stage IIIB or IV lung cancer received an EGFR-TKI as first-line therapy." (PMID 31655564, 2019). "Taken together, our findings suggest that mAChR3 might play an essential role in Arecoline-promoted EGFR/c-Src/Fak activation and migration in an A549 lung cancer cell line." (PMID 30925742, 2019). "For example, Liu and coworkers demonstrated that the delivery of vitamin D-based drug payloads via tumor-targeted epidermal growth factor receptor (EGFR) liposomal nanoparticles has promise as a new therapy of EGFR tyrosine kinase inhibitors for resisting lung cancer." (PMID 30641860, 2019). "Importantly, a previous study also reported a decreased rate of EGFR mutations in ctDNA after EGFR-TKI therapy, which was associated with the disease status in lung cancer patients." (PMID 31185703, 2019). "Moreover, down-regulation of miRNA-145 in lung cancer tissue correlates with high levels of EGFR, reducing tumor growth, inducing cell cycle arrest in the G1/S phase and enhancing the cytotoxic effects of anti-tumor agents." (PMID 31554377, 2019). "Importantly, the expression level of EGFR was significantly increased in TEX from lung cancer patients with respect to EX from normal individuals, which suggests that the measurement of TEX protein levels can be diagnostic for lung cancer." (PMID 30658453, 2019). "Indeed, EGFR-TKI-resistant (epidermal growth factor receptor-tyrosine kinase inhibitor) lung cancer cells presented a decreased methylation of the promoter of MAP1LC3v1 associated with increased LC3A protein expression." (PMID 31861179, 2019). "A Qiagen therascreen EGFR RGQ PCR kit (ARMS method) has been approved in the United States as well as Europe and Asian countries to detect EGFR mutations with high sensitivity and specificity in lung cancer tissues." (PMID 31185703, 2019). "Almost 40% patients will develop brain metastases during the course of their disease in non–small-cell lung cancer (NSCLC), and it may be even higher in those patients with epidermal growth factor receptor (EGFR) mutation." (PMID 31921625, 2019). "Overexpression of GAS5 could enhance the inhibitory effect of Gefitinib on EGFR phosphorylation and its downstream signaling activation, while enhancing the sensitivity of lung cancer cells to EGFR-TKI." (PMID 31750253, 2019). "Instead, quantification of exoRNA (KRAS mutant) might be of high interest as it was recently reported for detecting mutant EGFR in lung cancer." (PMID 31717747, 2019). "One of the other types of EGFR-blocking drug known as TKI, gefitinib is effective in the treatment of lung cancer with EGFR mutations; however, its benefits in HNSCCs are unknown." (PMID 31239839, 2019). "Here, the authors show that in lung cancer, genetic activation of distinct oncogenic receptor tyrosine kinases results in unique metabolic liabilities and, in particular, EGFR aberrant cancers rely on the serine biosynthetic pathway while FGFR aberrant cancers rely on glycolysis." (PMID 31221965, 2019). "In vitro experiment, EGFR activation mediated upregulation of PD-L1 in lung cancer cells could induce the apoptosis of T cells." (PMID 31552181, 2019). "H520 and H460 cell lines have lower EGFR expression compared with other lung cancer cell lines, such as A549 or CL1-0, which may be the reason why Arecoline administration did not stimulate their migration." (PMID 30925742, 2019). "Familial lung cancers tentatively favour adenocarcinoma, females, never-smokers, coexistence with secondary somatic EGFR mutation and occasionally multi-focal lesions." (PMID 31703574, 2019).
lung cancer (continued). "Recent studies showed that NCTD could overcome doxorubincin resistance in breast cancer cells and Hepatocyte growth factor (HGF) induced resistance to epidermal growth factor receptor tyrosine kinase inhibitors (EGFR-TKI) in lung cancer cells." (PMID 31120927, 2019). "A large cohort study of lung cancer patients reported favourable EGFR TKIs responses in patients who had G719 and L861, however, patients with other rare, uncommon EGFR mutations, failed to respond to kinase inhibitors." (PMID 31739412, 2019). "Thus, EGFRL858R/T790M/FGFR1 dual inhibitor 15c can be developed as an ideal candidate drug for FGFR1-amplified EGFR-TKIs resistant lung cancers." (PMID 31998131, 2019). "The development of EGFR TKIs has reformed the clinical management of lung cancer." (PMID 31637005, 2019). "Importantly, reduced NF1 expression has been also demonstrated to confer resistance to EGFR inhibition in lung cancer." (PMID 31226844, 2019). "Recently, several researches mentioned that the activation of the autocrine ring of FGF/FGFR, one of the typical RTKs, could act as a compensatory mechanism to promote the survival and growth of EGFR-TKIs resistant lung cancer cells." (PMID 31998131, 2019). "It should be considered that targeting the EGFR recycling pathway in combination with EGFR-TKI therapy may be an important strategy for lung cancer." (PMID 35582586, 2019). "In human lung cancer cells, EGFR inhibition activates autophagy as a cytoprotective response." (PMID 31514441, 2019). "Notably, of the overall cohort of EGFR T790M-positive lung cancer patients, 151 (8.2%) had EGFR C797S identified in their clinical cfDNA testing, considerably more frequent versus the 1.2% prevalence of L792 variants." (PMID 31632838, 2019). "In summary, while clinical studies are necessary to confirm these newly revealed dependencies of mutant EGFR in NSCLC, our genome-wide CRISPR-Cas9 genetic screen together with validation and mechanistic studies expanded the understanding of the heterogeneity of EGFR TKI responses in lung cancer." (PMID 31741433, 2019). "The aim of this study was to reposition FDA-approved drugs as part of combination therapy to overcome acquired resistance to EGFR TKIs in lung cancer and to tamoxifen in breast cancer, targeting their common mechanisms underlying off-target acquired resistance." (PMID 31993373, 2019). "The MDS results also align with the effects of tyrosine kinase inhibitors on ΔELREA and wild-type EGFR lung cancer cell lines, where more pronounced inhibition was observed against ΔELREA than for wild-type EGFR by inhibitors recognizing the active kinase conformation." (PMID 31536605, 2019). "Pyk2 promotes distinct cancers progression by regulating different downstream signaling pathways, and EGFR signaling pathway is found to be involved in Pyk2‐regulated downstream signaling pathways in liver cancer, breast cancer, lung cancer, MM, prostate cancer, bladder cancer, SCCHN, and glioma." (PMID 31368612, 2019). "However, no previous studies have examined the correlation between IGFBP7 and acquired EGFR-TKI resistance in lung cancer." (PMID 30609749, 2019). "EGFR is regulated by miR-145, which has been reported as a biomarker for acute pulmonary embolism, bipolar mania, temporal lobe epilepsy, breast cancer and lung cancer." (PMID 30717315, 2019). "Three patients in our study demonstrated uncommon EGFR mutations (2 with G719X+S768I, and 1 with S768I) and without T790M, exon 19 deletions or L858R mutations in the lung cancer tissues." (PMID 31185703, 2019). "Another important challenge of lung cancer therapy is the role of deregulated functioning of miR-23a and stem cells in making the lung cancer cells resistant to epidermal growth factor receptor-targeted tyrosine kinase inhibitors (EGFR-TKIs), commonly used for lung cancer treatment." (PMID 31530793, 2019).